KRT17 (keratin 17)
Diseases named in the same sentence as KRT17 in open-access papers (continued):
Sharing a sentence is not in itself a finding about the gene and the disease.
microhematuria (1 paper, 2024). "On the other hand, the average score of KRT17, cytology and microhematuria during the first 6 months after TUR was clearly able to predict recurrence-free survival while each marker alone did not." (PMID 38514751, 2024). "To further improve the diagnostic performance, we employed a simple algorithmic analysis of KRT17 in combination with cytology and/or microhematuria results." (PMID 38514751, 2024). "In this study, EV KRT17 and cytology/microhematuria scores during the first 6 months after TURBT (LV phase) were able to predictive recurrence-free survival and at least those with high EV KRT17 expression indicated a relatively poor survival though statistical significance wasn’t obtained." (PMID 38514751, 2024). "Among the biomarkers, MDK showed the best AUC, 0.760, for the detection of UBC, followed by KRT17 with AUC 0.730, and both EV mRNA markers outperformed conventional markers such as cytology (AUC 0.721), NMP22 (AUC 0.692), microhematuria (AUC 0.669) and BTA (AUC 0.659)." (PMID 38514751, 2024).
nasal polyps (1 paper, 2023). "KRT5 and KRT17 have been implicated in the regulation of cell proliferation and differentiation, and their upregulation may contribute to the abnormal growth of nasal polyps in ECRSwNP." (PMID 37867480, 2023).
rosacea (1 paper, 2025). A chronic erythematous skin disorder that affects the face. "Compared with healthy controls, KRT6A and KRT16 mRNA levels were significantly upregulated in rosacea, whereas CLDN1, CLDN16, OCLN, and KRT17 showed no significant changes, and CLDN23 was significantly downregulated." (PMID 40346694, 2025).
skin squamous cell carcinoma (1 paper, 2014). A carcinoma arising from the squamous cells of the epidermis. "In samples from human skin squamous cell carcinoma (SCC), Rac1 activity was higher in cancer tissues than in normal skin and activity correlated with keratin 17 overexpression." (PMID 24962779, 2014).
steatosis (1 paper, 2024). Increased lipid within the cytoplasm of cells. "To further investigate the effect of FFA-induced steatosis on KRT17 and ANXA2 expression, we assessed both the transcriptional and protein levels." (PMID 39273539, 2024).
tumor (181 papers, 2004 to 2026). "Thereafter, we detected an elevated expression of several tumor cell‐associated markers, including S100P, KRT17, KRT16, KRT7, and LY6D, as previously reported." (PMID 41164952, 2026). "KRT17’s association with T-lymphocyte infiltration suggests its role in enhancing anti-tumor immune responses." (PMID 41550766, 2026). "It detects keratin 17 (K17), a protein that is strongly associated with tumor cells and their proliferation." (PMID 40135048, 2025). "In mice, KRT17 is implicated in hair cycle regulation and tissue repair; genetic ablation inhibits tumour development and growth." (PMID 38165934, 2024). "Detectable circulating tumor DNA levels, high tumor keratin 17 expression, and mutational signature SBS15 were associated with decreased survival." (PMID 38900452, 2024). "KRT17 is significantly associated with clinical outcome of metastasis, tumor stage and 5-year survival in esophageal squamous cell carcinoma." (PMID 35706019, 2022). "Further studies found that positive KRT17 expression was associated with poor tumor differentiation, higher pT staging, more frequent distant metastasis, and a lower incidence of adenomas in the background." (PMID 35281081, 2022). "The high expression of KRT17 is associated with poor clinicopathological parameters of various malignant tumours, such as tumour size, depth of invasion, lymph node metastasis, tumour differentiation, distant metastasis and survival rate." (PMID 35281081, 2022). "The multivariate analysis showed a significant correlation between the risk for postoperative tumor recurrence, tumor grade as well as KRT17 positivity (each <0.001)." (PMID 31602265, 2019). "And finally, the neo-expression of KRT17 in aggressive growing conventional RCC is significantly associated with postoperative tumor relapse." (PMID 31602265, 2019). "In OSCC, KRT17 acts as a pathogenic keratin that facilitates tumor growth through the stimulation of multiple signaling pathways, highlighting the importance of KRT17 as a multifunctional promoter of tumorigenesis." (PMID 27512993, 2016). "Keratin 17 has been shown to be over-expressed in several adenocarcinomas including GC, and an association with aggressive tumor behaviour, local invasion, metastasis as well as treatment responsiveness has also been suggested." (PMID 24321518, 2013). "We assessed the clinical significance among the top DEGs using Oncomine database, and found that significantly increased KRT17 mRNA expression was closely associated with tumor tissues in multiple types of cancer including HNSCC when compared to their adjacent normal tissues." (PMID 35706019, 2022). "Moreover, KRT17 was strongly associated with tumor-infiltrating immune cells (such as macrophages, CD8+T, Tregs, and cancer-associated fibroblasts)." (PMID 35646078, 2022). "The Epi1 program was characterized by the expression of stress keratins (KRT6, KRT16, and KRT17) that are associated with keratinocyte hyperproliferation and therefore may play a role in enhancing tumorigenesis and tumor growth." (PMID 34489433, 2021). "Since increased KRT17 could activate and bind progesterone receptors (PR) and HER2, KRT17 overexpression was associated with a high tumor grade and positive axillary lymph nodes." (PMID 25874882, 2015). "The tumor diagnostic model was formulated as follows: logit (P-HCC) = -2.534 – 1.240 * SOCS2 expression level - 1.320 * LCAT expression level + 0.335 * FTCD expression level – 1.911 * KRT17 expression level + 4.422 * PBK expression level + 2.006 * CBX2 expression level." (PMID 36159831, 2022). "The tumor diagnostic model was formulated as follows: logit (P-HCC) = 6.906 - 0.494 * SOCS2 expression level - 1.250 * LCAT expression level – 0.493 * FTCD expression level + 0.602 * KRT17 expression level + 1.950 * PBK expression level + 7.243 * CBX2 expression level." (PMID 36159831, 2022).
tumor (continued). "Poor T-lymphocyte infiltration is considered a Key mechanism of tumor immune evasion, and Keratin 17 (KRT17) can increase T-lymphocyte infiltration to reverse the tumor immunosuppressive microenvironment." (PMID 40986143, 2025). "miR-485-5p directly suppresses KRT17 expression, diminishes tumor spheroid formation, and increases cellular sensitivity to cisplatin/carboplatin." (PMID 40710326, 2025). "To give an example, we focus on the target gene KRT17, producing a long non-coding RNA that is a main regulator in cell cycle and tumor proliferation." (PMID 40593827, 2025). "Targeting KRT17 or employing the Src inhibitor dasatinib can suppress tumor growth and improve chemotherapy sensitivity by obstructing the integrin/β-catenin pathway." (PMID 40710326, 2025). "IHC staining of subcutaneous xenografts revealed decreased KRT17 expression in tumor cells in the IL‐33‐knockdown group." (PMID 40860436, 2025). "For instance, the tumor subcluster 1_0 in Layer 2 is characterized by the marker gene KRT17, which is a recognized marker for PDAC." (PMID 40245302, 2025). "As validation, tumor epithelium showed upregulation of Krt17 and downregulation of Aldh3a1 relative to healthy tissue, confirming the neoplastic state." (PMID 41279770, 2025). "applied 10X Visium on 4 TNBC samples, showing that KLF5 expression co‐localised with basal markers (KRT5, KRT14, KRT17) in tumour regions, while areas with reduced KLF5 expression were enriched with CD4+ and CD8+ T cells." (PMID 40677104, 2025). "Meanwhile, IL‐33+ endothelial cells can up‐regulate the expression of KRT17 in EGC organoids to promote tumor growth." (PMID 40860436, 2025). "IL‐33 can upregulate the expression of endothelial adhesion molecules (PECAM1 and CD34) and organoid adhesion molecules (KRT17), thus promoting angiogenesis (cell‐to‐cell adhesion) and tumor proliferation." (PMID 40860436, 2025). "In contrast, genes with higher expression in HET/no pCR samples included basal cytokeratins (KRT5, KRT14, and KRT17), suggesting possible tumor subtype–related differences." (PMID 38300710, 2024). "The expression of KRT17 was significantly associated with shorter disease-free survival time in patients with stage II CRC, suggesting regulation of KRT17 was linked to tumor metastasis and recurrence." (PMID 38818308, 2024). "In tumor tissue however, KRT17 is well-known as an oncoprotein that promotes proliferation, immune evasion, survival, and other malignant hallmarks." (PMID 39358322, 2024). "MIHC of GBC-LI sections further revealed the CAF-enriched KRT17+ tumor region with a high neutrophil infiltration." (PMID 38822440, 2024). "Another important aspect of tumor progression is the role of keratin 17 in regulating glycolysis through its co-expression with HIF1α." (PMID 39194725, 2024). "Keratin 17 has been shown to be involved in regulating the proliferation, migration, and invasion of tumor cells." (PMID 39194725, 2024). "In the unpaired analysis, the KRT81, KRT6A, and KRT17 genes, which were positively associated with FSTL3 expression, exhibited notably elevated expression in tumor tissues in comparison to that in normal tissues." (PMID 38240936, 2024). "Suppression of keratin 17 expression can lead to the induction of tumor cell apoptosis through changes in the levels of Bcl-2 family proteins and enhanced regulation of caspase-3 cleavage." (PMID 39194725, 2024). "Normal peritumor epithelial cells expressed keratins 13 and 17, whereas in tumor tissue, the surface and invading epithelial cells retained the KRT17+ phenotype, but KRT13 expression disappeared." (PMID 38540309, 2024). "Normal mucosa attached to the surgically removed tumor piece showed KRT17 expression only in basal cells, which was downregulated upon tissue maturation." (PMID 39358322, 2024). "Expression of KRT17 was correlated with blood glucose (r = 0.204, p = 0.001) and tumor size (r = −0.177, p = 0.038) in patients." (PMID 38979664, 2024).
tumor (continued). "Previous studies in HNC link cytokeratin upregulation (including KRT17) with HPV-negative status or an ‘immune low’ subset of HPV-positive tumours." (PMID 39328208, 2024). "On the other hand, it was negatively correlated with tumor size; that is, the smaller the tumor, the higher the KRT17 expression level; otherwise, the KRT17 expression level decreased as the tumor grew larger." (PMID 38979664, 2024). "Four of them had significant expression in immune cells, SLC20A1 with KRT17 was more expressed in malignant tumor cells and ITGA1 was more expressed in mesenchymal cells." (PMID 39127853, 2024). "The most striking difference in BCC versus healthy epidermis was high expression of KRT17 in the nodules and invasive tumours." (PMID 38165934, 2024). "It suggests that this gene is significant in the early stages of a tumor, and the KRT17 screening test should be performed early when the tumor is small so that it can be detected as soon as possible." (PMID 38979664, 2024). "KRT17, a member of the intermediate filament family, has been shown to regulate the proliferation and migration of tumor cells." (PMID 37981694, 2023). "Keratin 17 (KRT17) is a type I keratin that is involved in multiple biological processes such as tumor growth and metastasis, inflammation, and signal transduction." (PMID 37634232, 2023). "The results showed that the tumor size was significantly increased in the KRT17 knockdown group compared to the control group (186.3 ± 43.2 mm3 and 67.8 ± 27.2 mm3, respectively)." (PMID 36765563, 2023). "PACpAInt-Comp was able to discriminate between GATA6 + /Claudin18+ versus KRT17+ areas, with AUCs of 0.87 and 0.75 for basal-like and classical tumor scores, respectively." (PMID 37311751, 2023). "On the contrary, the proliferation and metastasis ability of tumor cells were significantly decreased in Fadu and Detroit 562 cell lines overexpressed with KRT17." (PMID 36765563, 2023). "We also noticed that tumor proliferation was significant and the ability to invade and metastasize was substantially increased in the Detroit 562 cell line with KRT17 knockout compared to the control group." (PMID 36765563, 2023). "According to recent studies, Keratin 17 (K17) targets tumour suppressors and mediates signals to promote tumour growth." (PMID 37337404, 2023). "The expression of several race-associated genes was also dependent on the MED12 mutation status of the tumor, being higher (FRAT2, TNFRSF19, ACP7, IRS4, PLEKHG4B, KRT17, SLN, and ZNF703) or lower (CAV2) in the mutated specimens compared with wild-type tumors." (PMID 37686244, 2023). "Knockout or silenced KRT17 can inhibit the proliferation, migration, adhesion and invasion of tumour cells, and promote the apoptosis of tumour cells." (PMID 35281081, 2022). "We then analyzed the correlation between KRT17 expression in normal tissues and that in tumor tissues at different stages." (PMID 35646078, 2022). "Multivariate analysis showed that the positive expression of KRT17 in invasive conventional RCC was significantly correlated with postoperative tumour recurrence." (PMID 35281081, 2022). "OSCC tumor-bearing mouse model was established by generating stable KRT17-knockdown C9IV3 cells by shRNA that specifically targeted KRT17." (PMID 35706019, 2022). "KRT17 knockout can inhibit cell migration, proliferation and colony formation, induce cell apoptosis and cell cycle arrest, and inhibit tumour growth in xenograft mice." (PMID 35281081, 2022). "The results showed that KRT17 promoted tumour growth through the Akt/mTOR pathway and glucose uptake pathway." (PMID 35281081, 2022). "In OSCC xenograft mouse model, KRT17 knockdown significantly inhibited tumor growth, and combinatorial treatment with cisplatin elicited a greater tumor inhibitory effect." (PMID 35706019, 2022).
tumor (continued). "Another precedent is the cytoskeletal protein, keratin 17 (K17), which was identified inside the nucleus of tumor epithelial cells, promoting gene expression and cell proliferation." (PMID 35327648, 2022). "The results showed that knockdown of KRT17 or treatment with cisplatin significantly inhibited tumor growth, while cisplatin treatment in KRT17-knockdown xenografts elicited significant synergistic inhibition." (PMID 35706019, 2022). "The expression of SLC27A2, SFRP2, KRT17 were up-regulated in tumor tissues (p<0.05), the expression of TAGLN was down-regulated (p<0.05), while those of NAT2 remained unchanged (p>0.05), compared with the levels in the corresponding normal tissues." (PMID 36479114, 2022). "In future studies, we should investigate how KRT17 affects tumour growth or progression through the role of glucose uptake." (PMID 35281081, 2022). "Xenograft mouse tumor model was used to evaluate the effect of KRT17- knockdown in OSCC cells on tumor growth and drug sensitization." (PMID 35706019, 2022). "Compared with normal gastric tissue, the expression of KRT17 is higher in GC tissue, and the high expression of KRT17 is significantly positively correlated with tumour size, invasion depth, lymph node metastasis, clinical stage and vascular invasion." (PMID 35281081, 2022). "Of note, there were 90% of tumor tissues scored at moderate to strong expression of KRT17 from the stage III/IV specimens as compared to only 54% of tumor tissues were scored from the stage I/II specimens." (PMID 35706019, 2022). "The results of our TMA analysis indicated that KRT17 plays important roles in disease development depending on the HER2 level in the tumor." (PMID 36139022, 2022). "In OSCC, KRT17 is the downstream expressed gene of the glial-associated oncogene homologue 1 and 2 (GLI-1and GLI-2), Moreover, GLI-1 and GLI-2 can effect tumour growth by regulating KRT17 expression." (PMID 35281081, 2022). "Among them, keratin 1(K1) can act as a cell surface receptor in cancer, and KEGG enrichment analysis also shows that cytokine receptor action is more significant; while keratin 17 (K17) plays a role in DNA damage response and tumor initiation." (PMID 36300089, 2022). "When APC was overexpressed in SW116 cells with high KRT17 expression, tumor cell invasion and metastasis were inhibited to a certain extent, while the expression of β-catenin was significantly lowered." (PMID 34935584, 2021). "Nevertheless, care should be taken when interpreting these findings because TGF‐β can increase CSF2 in uterine epithelial cells, WNT7A in chondrocytes, KRT17 in tumor epithelial cells, and SERPINE1 in renal epithelial cells." (PMID 34789212, 2021). "At the same time, through the TCGA analysis of the characteristics of COAD patients, we found that the expression of KRT17 is correlated with age, tumor status, and TNM stage." (PMID 34935584, 2021). "LAMC2, an isoform of the laminin family, and the KRT14, KRT16, and KRT17 hemi-desmosomal proteins play crucial roles in tumor cell stability and filament formation anchorage, migration, and proliferation." (PMID 32922662, 2020). "We noticed that the expression of one gene, KRT17, which has been reported to stimulate the migration and invasion of the tumour cells, was significantly increased following ITGBL1 overexpression." (PMID 32537856, 2020). "Deletion of keratin 17 (KRT17) in basaloid skin tumor delays tumor initiation and growth, which is preceded by reduced inflammation." (PMID 33171868, 2020). "In cervical cancer cells KRT17 translocated from the cytoplasm to the nucleus where it is bound to p27 during the G1 phase of the cell cycle to increase tumor progression." (PMID 33171868, 2020). "When compared to Gli2tg animals, Gli2tg; Krt17−/− mice showed a delayed tumor onset, demonstrating that K17 plays an active role in tumor development." (PMID 31126068, 2019).